INS (insulin)
Diseases named in the same sentence as INS in open-access papers (continued):
Sharing a sentence is not in itself a finding about the gene and the disease.
tumor (continued). "Known effects of endurance exercise that can reduce tumor growth include a reduction in C-reactive protein (CRP) levels and the release of inflammatory markers such as IL-6, sex hormones, insulin response, and vascularization." (PMID 40362215, 2025). "Critically, CD40 expression was one of the distinguishing markers of the B cells infiltrating the tumour microenvironment, and the cell communication analysis highlighted the CD40LG (INS+ FOSlow, INS+) − CD40 (B cell) interaction." (PMID 40438247, 2025). "SACST assesses insulin secretion in response to calcium stimulation via vascular routes, while GLP-1 receptor imaging reflects receptor expression in tumor tissue." (PMID 40405975, 2025). "At the systemic level, metformin reduces hepatic gluconeogenesis and consequently lowers circulating insulin concentrations, thereby attenuating activation of insulin- and IGF-1-dependent signaling cascades that are frequently co-opted in tumor growth." (PMID 41157306, 2025). "Insulin and insulin-like growth factor 1 (IGF-1) are potent promoters of cell proliferation and tumor cell survival." (PMID 41178954, 2025). "For example, insulin can directly activate the PI3K/AKT/MTOR/S6K signaling pathway in tumors, and promote the increase of NF-KB to regulate cell proliferation and tumor metastasis." (PMID 40756516, 2025). "The final approach for characterizing molecular mediators of tumor cell responsiveness based on CS grade was to examine the effects of SMI1182, DOX, and BEZ on insulin/IGF/IRS signaling downstream through mTOR networks using multiplex ELISA platforms." (PMID 40427168, 2025). "As a PIP3-dependent Rac-GEF, P-Rex2 mediates insulin/PI3K signalling, and as an inhibitor of the tumour suppressor Pten, it regulates PIP3 levels." (PMID 40764335, 2025). "High glucose concentration, insulin, and hypoxia upregulate GLUT12 both in adipocytes and tumor cells." (PMID 38727993, 2025). "Tumor-derived cytokines, notably IL-6 and tumor necrosis factor α (TNF-α), contribute to adipose tissue inflammation, impairing insulin sensitivity." (PMID 41397158, 2025). "Enhanced GLUT1 expression and oncogenic insulin signaling drive elevated glucose uptake in HNSCC, which contribute to the maintenance of redox homeostasis and tumor growth." (PMID 40371988, 2025). "CR promotes metabolic reprogramming by inducing a state of low energy availability that sensitizes tumor cells, which, according to the literature, is due to the inhibition of crucial oncogenic pathways such as IGF-1 and insulin signaling." (PMID 41514622, 2025). "In BC, IRS-1 and its phosphorylated form (p-IRS1) are key mediators in the insulin and insulin-like growth factor (IGF) signalling pathways and play crucial roles in the cellular signalling pathways influencing tumour progression and treatment response." (PMID 38474001, 2024). "The immunohistochemistry (IHC) studies performed showed the tumor was positive for CKA1AE3, chromogranin, synaptophysin, and focal positivity for insulin." (PMID 39104820, 2024). "Given that mitochondrial autophagy provides beneficial regulatory effects through low insulin signaling, increased insulin/IGF signaling can induce mitochondrial autophagy in certain types of tumors, thereby inhibiting tumor progression." (PMID 39763653, 2024). "Blood glucose and serum insulin, IGF-1 and IGFBP3 were measured at study end when tumor volumes reached 800 mm3." (PMID 38082056, 2024). "In contrast with these observations, calorie restriction decreases tumor growth in mouse models, attributed to reduced insulin and IGF-1 levels and enhanced tumor immunity." (PMID 38831236, 2024). "To assess if whd is regulated by insulin signalling, we knocked down FOXO via RNAi in the muscle of tumour-bearing animals (QRasV12scribRNAi), and found the whd transcription was significantly downregulated." (PMID 38429578, 2024). "For example, insulin and IGF-I activate PI3K/Akt/mTOR and Ras/Raf/MAPK signaling pathways, thereby stimulating tumor growth." (PMID 37954072, 2023).
tumor (continued). "We identified two mechanisms through which the fasting-induced reduction in insulin, IGF1 and leptin cooperates with CBIs to lower intratumour cholesterol and to slow tumour growth." (PMID 37907500, 2023). "Insulin can stimulate the synthesis of IGF-I, both of which have strong mitogenic effects on tumor cells." (PMID 37954072, 2023). "In addition to the risk of hypoglycemia, insulin can also result in false-negative tumor detection." (PMID 37884546, 2023). "IGF studies have indicated oncogene transformation, tumor proliferation, and tumor growth regulation by type 1 IGF receptor (IGF-1R), IGF-1, and insulin, identifying IGF signaling a viable therapeutic target." (PMID 37373357, 2023). "That is, high concentrations of insulin, combined with IGF-I, can initiate the PI3K/Akt and MAPK signaling pathways, inhibit tumor cell apoptosis, and promote cell proliferation." (PMID 36672448, 2023). "In contrast, intrinsic insulin secretion and extrinsic high insulin levels induce strong FDG uptake in myocytes, which results in images that are unsuitable for evaluating tumor distribution with diffusely increased muscular uptake." (PMID 36575286, 2023). "In Esg>yki[S3A] thoraces, a setting of reduced insulin signaling, REPTOR expression was enhanced by tumor-derived ImpL2." (PMID 37582831, 2023). "In the glucose-free dulbecco’s modified eagle medium (DMEM), D-glucose, L-glucose and insulin were added, respectively, to study their effects on the uptake of [99mTc]Tc-CNMCHDG in A549 tumor cells." (PMID 37111368, 2023). "Increased uptake of glucose by tumor cells would raise the ATP/ADP ratio, leading to the inhibition of ATP-sensitive potassium channels and triggering a cascade to secrete insulin." (PMID 37834179, 2023). "Kyoto Encyclopedia of Genes and Genomes (KEGG) pathway enrichment analysis also revealed that a lot of DDX5-regulated circRNAs are mainly enriched in tumor-related signaling pathway, including VEGF and insulin signaling pathway." (PMID 36996491, 2023). "Both insulin and IGF play pivotal roles in instigating various mechanisms that foster tumor growth, encompassing cellular proliferation and differentiation, angiogenesis, and anti-apoptosis." (PMID 38068717, 2023). "Tumours secreting big IGF-II are characterised by an increased total IGF-II:IGF-I ratio, hypoglycaemia with suppressed insulin and C-peptide and inappropriately low GH and β-OHB levels." (PMID 37892096, 2023). "Studies using Drosophila and Drosophila melanogaster models have shown that ImpL2 secreted by tumor, a homologue of IGF binding protein and a potent antagonist of insulin signaling, leads to systemic metabolic impairment and muscle wasting." (PMID 36105371, 2022). "When treated with insulin lowering methods, including SGLT-2 inhibitor and the ketogenic diet, the tumor cells had a better response to PI3K inhibitors." (PMID 35252207, 2022). "We thus concluded that tumor cells, especially in the G2 stage, are sensitized for IGF1, IGF2 and Insulin stimulation by increased glucose in the TME, as these growth hormones can activate IGF1R." (PMID 35574343, 2022). "Both insulin and IGF induce a multitude of tumor-promoting mechanisms involved in cell proliferation, anti-apoptosis, angiogenesis, and lymphangiogenesis." (PMID 35053431, 2022). "LAIR-1+Tc% was correlated with the HCC surrogate tumor marker AFP (r = 0.367, p = 0.001) and insulin resistance and inflammation prognostic ratios/indices." (PMID 36293412, 2022). "High levels of insulin and insulin-like growth factor (IGF)-1, expressed under the action of carbohydrate-rich food, can contribute to the proliferation of tumor cells through the insulin signaling pathway/IGF1." (PMID 35625744, 2022). "High glucose levels can increase PD-L1 expression in tumor cells for tumor immune evasion by HK2-mediated NFκB activation and pancreatic insulin secretion, which in turn can activate PI3K-AKT in tumor cells to increase the Warburg effect." (PMID 39872073, 2022).
tumor (continued). "KD can affect tumor cell growth by lowering insulin and IGF-1 levels, thereby reducing receptor tyrosine kinase-dependent signaling pathways such as PI3K-Akt-mTOR for tumor cell proliferation and tumor growth." (PMID 36432618, 2022). "Based on these two signal pathways, insulin enhances PDA development through mediating metabolic reprogram, crosstalk with IGF-1, strengthening drug resistance, and stimulating tumor microenvironment (inflammation, fibrosis, and neo-angiogenesis) formation." (PMID 35252207, 2022). "Non-tumor-bearing KPC7−/− animals featured an overabundance of pre-malignant PanIN lesions and reduced insulin producing cells in the islets of Langerhans." (PMID 35372352, 2022). "Similar to IGF-1, insulin levels were significantly increased in HFD mice compared to both NCD and CR at tumour endpoint." (PMID 35908046, 2022). "High insulin levels also reduce IGF-1-binding proteins and increase free-IGF-1, overactivating the mitogenic effects of the IGF-1 pathway in tumour tissues." (PMID 35681699, 2022). "We studied the effects of 6 common antidiabetic drugs on tumor inhibition of anti-PD1 immune checkpoint inhibitor, including acarbose, sitagliptin, metformin, glimepiride, pioglitazone, and insulin." (PMID 36033393, 2022). "This phenomenon, that in C26 tumor bearing mouse models manifests even before the cachexia phenotype is observed, is mainly dependent on TNF-α, which directly impairs insulin signaling and IRS-1 activation." (PMID 35441960, 2022). "Insulin /IGF axis is an important pathway for the proliferation of normal thyroid cells and tumor cells." (PMID 35711846, 2022). "GB cells project tumor microtubes (TMs) contact with neurons, and exchange signaling molecules related to Wingless/WNT, JNK, Insulin or Neuroligin-3 pathways." (PMID 35877760, 2022). "PTPRN2, a gene involved in insulin secretion, and MAD1L1, which plays a role in the cell cycle and tumor suppression, contained DMRs in males and females in both cohorts." (PMID 35500004, 2022). "Some cancerous animal models displayed a decrease in systemic insulin due, in part, to high amounts of IDE released by tumor cells." (PMID 35406791, 2022). "Upregulated expression of the proliferative marker Ki67 was found in tumor tissue sections obtained from E2 and insulin‐treated mice relative to those exposed to ICI or OSI‐906 either alone or in combination with E2 and insulin." (PMID 34841688, 2021). "In the TCGA dataset, phaeochromocytoma expresses higher levels of INS and INS-IGF2 transcripts compared to the normal non-tumour adrenal glands." (PMID 34170845, 2021). "While the effects of insulin and IGF on tumor cell growth have been recognized already, their role in the acquired immune privilege in PDAC is not known yet." (PMID 34202040, 2021). "Insulin increases the breakdown of IGFBP-3, thus increasing the levels of free IGF-1, promoting tumor formation." (PMID 34359595, 2021). "For instance, curcumin induces transcriptional activation of the tumor-suppressive micro RNA miR-34a, which is paralleled by downregulation of MYC, β-catenin, insulin, and IGFR mRNAs." (PMID 33937075, 2021). "We found an unexpected increase in tumor insulin sensitivity in the HFHS regimen, leading to enhanced tumor growth, and this was accompanied by the upregulation of genes involved in EMT, angiogenesis, and metastasis." (PMID 34162829, 2021). "Insulin and IGF-1 also stimulate β-catenin, a signaling pathway involved in early tumor formation, and the Ras oncogene." (PMID 34359595, 2021). "The binding of insulin or free insulin-like growth factor IGF-1 to specific tyrosine kinase receptors can activate the insulin/IGF-1-PI3K-Akt-mTOR signaling pathway and enhance glycolysis and glutamine breakdown, thereby promoting tumor cell proliferation." (PMID 33918992, 2021).
tumor (continued). "Before stopping alpelisib treatment, which showed good anti-tumor efficacy, we decided to use the most recent class of antidiabetic drug (SGLT2 inhibitors) which acts independently of insulin signalling." (PMID 34281618, 2021). "At the systemic level, metformin suppresses insulin/IGF-1 and nuclear factor-κB (NF-κB) signaling pathways, downregulates the release of proinflammatory cytokines and augments CD8+ T cell anti-tumor responses." (PMID 34502231, 2021). "Moreover, data from RCTs with traditional therapies such as insulin, thiazolidinedione (TZD), and sulfonylurea (SU) associated with body weight gain made it possible to evaluate the relationship between weight elevation and the incidence of neoplasms by intervention studies." (PMID 33424764, 2020). "BRD7 was initially recognized as a tumor suppressor, but recent studies have provided evidence that BRD7 participates in the regulation of metabolism and insulin signaling pathway with detailed mechanistic underpinnings." (PMID 32992509, 2020). "Tumor-induced inflammation has been shown to promote the alteration of liver circadian homeostasis, altering AKT, AMPK and SREBP signaling, as well as insulin and glucose homeostasis." (PMID 33202621, 2020). "This implies that tumor-bearing in HFD-fed mice tends to decrease body mass, epididymal fat mass, plasma glucose, plasma insulin, plasma leptin, and insulin resistance, while elevating plasma glutamine." (PMID 32121098, 2020). "In turn, IR-A–mediated biological responses are regulated by tumor stroma components, such as the proteoglycan decorin, which negatively modulates IGF-2 actions while leaving unaffected insulin/proinsulin effects." (PMID 33364239, 2020). "The evidence also suggests that IGFBPs perform insulin/IGF-independent functions, including in the course of tumor progression." (PMID 32500027, 2020). "Aspirin mitigated the increments of glucose, insulin, leptin, WBC, neutrophils, lymphocytes, glutamine, soluble P-selectin, and TGF-β1 in tumor-bearing HFD-fed mice." (PMID 32121098, 2020). "While only a subset of ARX+ tumours secreted glucagon (n = 7, 20% of all the ARX+ tumours), almost all the PDX1+ tumours produced insulin (n = 18, 95% of all PDX1+ tumours)." (PMID 33288854, 2020). "Next to its well-documented function in tumor development and progression, the miR-200 family regulates key players (e.g. FOG2, Rheb) in the insulin signaling pathway." (PMID 32109241, 2020). "The use of PI3K inhibitors, in combination with insulin-lowering therapies, such as a ketogenic diet or sodium glucose co-transporter-2 (SGLT2) inhibition, resulted in sustained suppression of tumor growth in pre-clinical studies." (PMID 33604295, 2020). "Based on H & E and insulin and glucagon immunoreactivities, MPM mice exhibited the same multi-step tumor progression from hyperplastic islets to one tumor to more tumors as observed in the MPR mice." (PMID 31160716, 2020). "In short, the excessive insulin in patients with metabolic syndromes facilitates these metabolic pathways in the TME, which potentiates tumor growth and compromises antitumor activity." (PMID 32512898, 2020). "Insulin also induces the overstimulation of receptors of insulin-like growth factor-1 and 2 (IGF-1 and IGF-2), a key promoter of tumor development." (PMID 33238496, 2020). "Research supports the role of insulin and IGF-1 as important growth factors, acting through the tyrosine kinase growth factor cascade in enhancing abnormal tumor growth." (PMID 31719636, 2019). "Fixation and sectioning of RT2-Tomato tumours confirmed that RT2 tumours grew on top of the iris, and that tdTomato fluorescence correlated with insulin staining." (PMID 31601958, 2019). "These tumors may secrete excessive quantities of hormone such as gastrin, insulin, vasoactive intestinal polypeptide (VIP), glucagon, or somatostatin and may be associated with distinct clinical syndromes, with approximately one third of these neoplasms becoming clinically apparent." (PMID 31263451, 2019).
tumor (continued). "In these patients, early diagnosis of prostate cancer is hampered because blood levels of prostate-specific antigen (PSA) are low, due to insulin and IGF levels, despite tumor proliferation." (PMID 31284513, 2019). "There is evidence for the role of αvβ3 heterodimer in multiple mechanisms of tumor growth and invasion, including interaction with ECM components, matrix metalloproteinase 2, platelet-derived growth factor, insulin, VEGF receptors, and prevention of apoptosis." (PMID 31832016, 2019). "β-elemene significantly suppressed the insulin-driven cell growth and the activation of mTOR and PI3K in tumor cells, while the toxicity to normal hepatocytes was much lower." (PMID 30422809, 2019). "Our results on intervention in the insulin/INSR signalling axis by siRNA and antibody-mediated targeting in vitro and in vivo demonstrate the capacity of this pathway to regulate tumour angiogenesis." (PMID 30559346, 2019). "Since EGF, bFGF, and insulin are the three main components in our sphere-formation pelletizing system, which also exist in the tumor microenvironment, we exposed MCF-7 cells to EGF, bFGF, or insulin separately." (PMID 30792382, 2019). "Next, we aimed to identify the source of insulin and IGF-1 receptors ligands, namely IGF-1 and IGF-2, in the tumor microenvironment." (PMID 29367764, 2018). "KLa has tumor-suppressing roles on cell proliferation and survival, resulting from inhibition of the IGF-1/insulin signaling pathway and EMT." (PMID 29731962, 2018). "There is substantial evidence implying that insulin and insulin-like growth factor (IGF) signaling axis prompt PDAC into an advanced stage by enhancing tumor growth, metastasis and by driving therapy resistance." (PMID 29475434, 2018). "Studies carried out in normal and tumor thyrocytes have especially highlighted the importance of the functional crosstalk between TSH-cAMP and insulin/IGF axis, which occurs at multiple levels." (PMID 29184536, 2017). "PRAS40 is phosphorylated in response to insulin or IGF-1 treatment, and plays an important role in the tumor cell proliferation induced by these growth factors." (PMID 28978182, 2017). "Preclinical studies found that metformin reduces insulin and IGF-1 level in serum and stables blood glucose level through AMPK pathway and thus reverses the tumor promoting effect driven by hyperinsulinemia and hyperglycemia." (PMID 28271076, 2017). "A recent study showed that insulin treatment prevented the increased expression of ATGL and HSL in the retroperitoneal white adipose tissue, as well as increased the food intake of tumor-bearing rats." (PMID 28830524, 2017). "Both insulin and IGF1 are promoters of cell proliferation and inhibition of apoptosis in tumor cells." (PMID 28954281, 2017). "Metformin decreases insulin and IGF-1 levels and stables blood sugar level by activating AMP-activated protein kinase (AMPK), thus preventing tumor cells from growing." (PMID 28271076, 2017). "It is the only medical treatment that can suppress tumor production of IGF2, leading to normal levels of C-peptide, insulin and glucose." (PMID 27134683, 2016). "One possible explanation for this result involves the addition of insulin in the cell culture medium of RL95-2 cells, which is recommended by ATCC, as insulin protects tumor cells from apoptosis." (PMID 27711077, 2016). "The pathophysiology of NICTH arises from excessive tumor production of both IGF-II and its precursor “big” IGF-II, resulting in an altered IGF-I to IGF-II ratio and insulin-independent stimulation of the insulin receptor." (PMID 27905899, 2016). "However, the major cause of NICTH could be as follows: increased glucose utilization by large tumors, inhibition of glycogenolysis and gluconeogenesis from the liver, and suppression of counterregulatory hormones for insulin or insulin-like factors secreted by the tumor." (PMID 27957352, 2016).